IL1B (interleukin 1 beta)
Diseases named in the same sentence as IL1B in open-access papers (continued):
Sharing a sentence is not in itself a finding about the gene and the disease.
Sepsis (continued). "Active NLRP3 promotes the secretion of the cytokines IL-1β and the cysteine proteases (caspase-1), which are considered protective during initial process of sepsis." (PMID 30779706, 2019). "The secretion of proinflammatory cytokines, such as TNF-α and IL-1 (including IL-1α and IL-1β), in sepsis has been demonstrated in numerous studies." (PMID 31333903, 2019). "Our previous study showed sepsis-induced increase in IL-1β level in the hippocampus peaked at 7 days after CLP." (PMID 31354429, 2019). "As expected, sepsis induced an acute increase in both inflammatory (TNFα, IL1β, IL-6) and anti-inflammatory (IL-10) plasma cytokine concentrations." (PMID 31248453, 2019). "IL-1β plays a major role in local acute inflammation, which is regarded as a panic cytokine of sepsis." (PMID 31234591, 2019). "Studies have shown that the uncontrolled production of pro-inflammatory cytokines, such as TNF-α and IL-1β, plays a key role in the development of sepsis." (PMID 30967878, 2019). "In horses, IL-1β elevations have been documented in foals with naturally occurring sepsis and in adult horses following LPS infusion." (PMID 30931316, 2019). "Alternative pathways of GC synthesis have been reported in sepsis or mental diseases, in which interleukin (IL)-1β, prostaglandin E2 (PGE2), and/or cAMP-activated guanine nucleotide exchange factor 2 (EPAC2) are likely to play a role in this regard." (PMID 31998227, 2019). "It is possible that an initial release of IL‐1β had occurred already before collection of the first study sample, as IL‐1β is known to be present during the early phase of bacteremia or sepsis." (PMID 31403210, 2019). "α-1-antichymotrypsin also acts as a negative regulator of pro-inflammatory cytokine production (e.g., TNF-α and IL-1β) and innate immunity, thus protecting against systemic inflammation (i.e., lethal endotoxemia and sepsis)." (PMID 31001142, 2019). "For example, the administration of miR-146a was found to reduce proinflammatory cytokines (TNF-α, IL-1β, and IL-1α) and inflammatory edema in an LPS-induced model of sepsis in rats by targeting the TLR-4/NFκB pathway." (PMID 31671621, 2019). "Meanwhile, deficiency of SESN2 showed defective mitophagy, caspase-1 hyperactivation, and increased secretion of IL-1β and IL-18, which ultimately increased the mortality in murine sepsis." (PMID 31867002, 2019). "We found that FoxP3 was more expressed by treatment with high (10 ng/mL) than low dose (10 pg/mL) of IL-1β, raising a possibility of IL-1β induced CD4 T-cell differentiation to regulatory T cells in sepsis." (PMID 31323786, 2019). "Another important cytokine during sepsis in humans and horses is IL-6, which is produced after cells are exposed to TNFα and IL-1β." (PMID 30931316, 2019). "In fact, lower mortality was observed in rats exposed to LPS and treated with a monoclonal antibody against TNF-α, and beneficiary effects were also observed for anti-IL-1β as well as anti-IL-6 antibody treatment in other experimental models of sepsis." (PMID 31075981, 2019). "Previous studies have shown that resveratrol can suppress NLRP3 and subsequent IL-1β in sepsis models." (PMID 30691208, 2019). "LPS-injected Rag2 KO rats developed sepsis as indicated by increased TNFa, IL-6, IL-1b, and IL-10 levels and thrombocytopenia." (PMID 31921873, 2019). "Caspase 1 activity and secretion of IL‐1β by platelets were assessed to confirm activation of the NLRP3 inflammasome in platelets after induction of sepsis in CLP rats." (PMID 31054188, 2019). "At 72 HPI, sepsis appeared to have progressed, with an increase in serum IFNγ, IL1β, IL10, and TNFα." (PMID 31121001, 2019). "In this study, we also observed that VU0155069 administration strongly induced therapeutic effects against polymicrobial sepsis, whose pathological progress is also mediated by increased IL-1β." (PMID 31586128, 2019).
Sepsis (continued). "MRSA-mediated induction of the sepsis-associated molecule C-reactive protein (CRP), the proinflammatory cytokines IL-6, IL-1β, and TNF-α were also attenuated by Epi-1 treatment." (PMID 31835381, 2019). "Based on our results of the possible role played by mucosal DC-producing IL-1β during sepsis, we proposed a model to illustrate the compartmental differences DCs in systemic SP and mucosal MLN organs exert vis-à-vis CD4 T-cell proliferation." (PMID 31323786, 2019). "A limitation of many of these studies with cultured islets is that pharmacological IL-1β concentrations were used, which exceed both physiological IL-1β concentrations and levels reached in extreme models such as sepsis." (PMID 30989320, 2019). "MEG3 was recently reported to bind miR‐138 and derepress IL‐1β, intensifying the reaction of macrophages to bacterial infections of the lung and preventing sepsis." (PMID 31496026, 2019). "Although significantly upregulated in LPS-induced sepsis, miR-146b seems to suppress the inflammatory processes involved, as portrayed by a reduction of IL-1β and cellular apoptosis, probably by targeting Notch1." (PMID 31671621, 2019). "VU0155069 strongly enhances survival rate in cecal ligation and puncture (CLP)-induced sepsis by inhibiting lung inflammation, leukocyte apoptosis, and the production of proinflammatory cytokines, especially IL-1β." (PMID 31586128, 2019). "Our study indicated that the serum cytokines such as TNF-α, IL-1β, and IL-6 were inhibited by hydrocortisone, which were consistent with previous studies in both animals and humans with sepsis." (PMID 31880211, 2019). "We observed an increased unstimulated production of IL-6 and IL-1β in the time of sepsis, which further increased after LPS stimulation, demonstrating an unskewed ability to synthetize these cytokines." (PMID 31781117, 2019). "And its low expression was associated with advanced disease severity (APACHE II score and SOFA score) and systemic inflammation (CRP, PCT, TNF‐α, IL‐1β, IL‐6, and IL‐17) in sepsis patients." (PMID 31206807, 2019). "Treatment with KRN shortly after sepsis induction resulted in a worsening of systemic inflammation, with a further elevation in IL-6 levels (58 ± 5 ng/ml) and a significant increase in IL-1β levels (439 ± 27 pg/ml)." (PMID 29720984, 2018). "This study showed that the effects of IL-6 were independent from the effects of TNF-α, IL-1β, and IL-12, but IL-6 was regulated by ILT4, which was associated with poor prognosis of sepsis." (PMID 29662678, 2018). "Ten hours after sepsis induction, vehicle-treated pups demonstrated a significant increase in serum levels of IL-6 and IL-1β compared to sham pups (55.9 ± 4.2 vs. 0.1 ± 0.1 ng/ml and 377.2 ± 42.6 vs. 4.6 ± 2.6 pg/ml, respectively)." (PMID 29720984, 2018). "We found that a nonlethal dose of LPS, corresponding to an established animal model of sepsis, enhanced the circulating levels of IL-1β and IFN-γ assessed by cytokine array." (PMID 29928698, 2018). "In mammals including humans, there is a so called “cholestasis of sepsis”, in which systemic pro-inflammatory cytokines like IL-1β and TNF-α lead to downregulation of bile acid transporter proteins and to canalicular and ductular cholestasis." (PMID 30149505, 2018). "Treatment with A‐438079 after the onset of sepsis abrogated the rise in serum creatinine at 24 h with reduced renal IL‐1β expression early." (PMID 29488356, 2018). "TNF-α and IL-1β were measured to assess the presence of neuroinflammation in the cortex and hippocampus of the sepsis survivors." (PMID 30186119, 2018). "TNF-α, interleukin-1β (IL-1β), IL-6, and monocyte chemotactic protein-1 (MCP-1) are hallmark inflammatory mediators of sepsis that constitute the cytokine storm." (PMID 29980671, 2018). "Inflammatory cytokines, including tumour necrosis factor (TNF)-α, interleukin (IL)-1α, IL-1β, and IL-6, promote the development of sepsis-induced cardiomyopathy." (PMID 29693453, 2018).
Sepsis (continued). "Here, we demonstrate that omega-9 treatment is associated with increased levels of the anti-inflammatory cytokine IL-10 and decreased levels of the proinflammatory cytokines TNF-α and IL-1β in peritoneal lavage fluid of mice with sepsis." (PMID 30538802, 2018). "Equilibrium between TNF-α, IL-1β and anti-inflammatory IL-10 has been proven highly dynamic and dependent on genetic heterogenity in human sepsis and SIRS." (PMID 29304171, 2018). "Ten hours after sepsis induction, expression of IL-6 and IL-1β as well as the neutrophil chemoattractants KC and MIP-2 in the lungs of neonatal mice were measured." (PMID 29720984, 2018). "Both HMGB1 and IL-1β have been found to play critical roles in sepsis and post-burn immune dysfunction." (PMID 29601597, 2018). "High levels of TNF-α and IL-1β in sepsis are generally considered to be correlated with high mortality, while IL-12, the primary effector of monocytes, can synergize IFN-γ to promote the inflammatory response, leading to poor prognosis of sepsis." (PMID 29662678, 2018). "Both the DAMP High-Motility Group Box-1 (HMGB1) and the cytokine IL-1β have been found to play critical roles in sepsis and post-burn immune dysfunction." (PMID 29601597, 2018). "The effects of TNF-α and IL-1β in sepsis are amplified, leading to the recruitment of more inflammatory cells into the alveolar injury site." (PMID 29462936, 2018). "Similar results were obtained for the levels of the proinflammatory cytokines, TNF-α and IL-1β, indicating that SIRT3 knockout increased inflammatory responses associated with sepsis-induced AKI through the AMPK/mTOR/autophagy pathway." (PMID 30487750, 2018). "The level of TNF-α and IL-1β in sepsis group was markedly higher than the sham group in both 24 and 96 h post LPS injection." (PMID 28250969, 2017). "IL-1A, interleukin-1 beta (IL-1B), and IL-8 were significantly downregulated in septicemic melioidosis patients compared to their expression in other sepsis cases." (PMID 28435890, 2017). "IL-1β is a key cytokine in sepsis during which the plasma levels of the cytokine can become exceedingly high." (PMID 28428949, 2017). "Our study is the first to demonstrate that GIK decreased the rate of mortality in a rat model of sepsis, decreased the production of intestinal tissue proinflammatory cytokines, including IL-1β, IL-6 and TNF-α, and increased the level of IL-10." (PMID 28428961, 2017). "Other studies have suggested that IL-6, in association with IL-1β, is implicated in the NOS-dependent systemic vasodilatation seen during sepsis." (PMID 28424078, 2017). "Sepsis was associated with increased TNF-α and IL-10 levels in the hypothalamus and higher IL-1β, IL-6, and IL-10 in the brainstem." (PMID 27229490, 2017). "While plasma IL-6, TNF-α, and IL-1β levels are also reported as predictors of death from sepsis, in our study the utility of IL-8 was much greater." (PMID 28167592, 2017). "We performed qRT-PCR to investigate if sepsis increases Il1b or Nlrp3 expression in gastrocnemius/plantaris or tibialis anterior muscle of mice and found that sepsis induced Il1b and Nlrp3 expression in both muscles." (PMID 28097512, 2017). "Of these cytokines, tumor necrosis factor-α (TNF-α) and interleukin-1β (IL-1β), which are produced excessively at the early stages of sepsis, have been found to depress cardiac function synergistically." (PMID 28270914, 2017). "In parallel with these forebrain cholinergic alterations, microglial activation (in the cortex) and increased Il1b and Il6 gene expression (in the cortex), and Il1b gene expression (in the hippocampus) were observed in mouse sepsis survivors." (PMID 29326685, 2017). "We found that plasma concentrations of TNF-α, IL-1β and IL-6 in the sepsis group were significantly higher than in the healthy control group, and the levels of these cytokines also increased with sepsis severity." (PMID 28472164, 2017).
Sepsis (continued). "Following massive microbial infection, highly produced inflammatory cytokines, mainly TNF-α and IL-1β, drive hyperinflammation in sepsis patients." (PMID 28533774, 2017). "In the present study, TNFα, IL-1β and IL-6 transcript levels were all increased in gastrocnemius and diaphragm muscles during sepsis, but this response was significantly greater and more sustained over time in the diaphragm muscle." (PMID 28883493, 2017). "The plasma concentrations of TNF-α, IL-6 and IL-1β were significantly higher in the sepsis patients compared to the healthy volunteers (P < 0.0001), and that they increased with the aggravation of sepsis (P < 0.05)." (PMID 28839236, 2017). "Pro-inflammatory cytokines including tumor necrosis factor α (TNFα), IL-1β, IL-6, and IL-8 are potent immune mediators that exacerbate multiple equine diseases such as sepsis and laminitis." (PMID 29034249, 2017). "Interleukin-1β (IL-1β), IL-6, IL-10 and tumor necrosis factor-α (TNF-α) are some of the classical sepsis-associated cytokines." (PMID 28176831, 2017). "Here, we demonstrate that IL-1β production during sepsis with uropathogenic E. coli is mediated by caspase-8, since caspase-8 and RIPK3 double knock out mice show substantially lower cytokine during sepsis and increased survival after injection of TNFα." (PMID 28428949, 2017). "Supporting this idea, it was also found that IRAK1-deficient mice exhibit markedly lower levels of interleukin- (IL-) 6 and IL-1β and suffer from significantly less sepsis-induced mortality." (PMID 28680194, 2017). "As NLRP3-dependent release of IL-1β has a critical role in sepsis, the in vivo activity of scutellarin was assayed in a mouse model of bacterial sepsis, which was established by intraperitoneally injection of a lethal dose of viable Escherichia coli." (PMID 29375379, 2017). "Among the three sepsis subgroups, the plasma concentrations of TNF-α, IL-6 and IL-1β in the severe sepsis/septic shock subgroups were significantly higher compared with the mild sepsis subgroup." (PMID 28472164, 2017). "Accumulating evidence demonstrates that the inhibition or specific antagonism of MCP-1 results in decreased release of TNF-α, IL-1β and IL-6 by macrophages and confers survival benefits on mice following sepsis." (PMID 28472164, 2017). "In the early stages of sepsis, large amounts of proinflammatory cytokines including IL-1β, known as ‘cytokine storm,’ are produced leading to multiple organ injury and failure." (PMID 29375379, 2017). "Pro-inflammatory cytokines like TNF-α, IL-1β, and IL-6 are responsible for severe manifestations in sepsis and septic shock." (PMID 27430881, 2016). "NAC infusion to rats with sepsis resulted in reduced oxidative stress, neutrophil density, and IL-1b." (PMID 27974950, 2016). "It is suggested that the higher levels of proinflammatory cytokines have a protective effect because a previous injection of IL-1β showed improved survival in a murine sepsis model." (PMID 27478305, 2016). "Citrulline supplementation reduced the release of TNF-α, IL-6, and IL-1β in the early stages of sepsis." (PMID 27195281, 2016). "This suggested that citrulline supplementation reduced the release of TNF-α, IL-6, and IL-1β in the early stages of sepsis." (PMID 27195281, 2016). "And some reports indicated that NF-κb pathway was activated during sepsis and increased expression of proinflammatory cytokines such as IL-6, IL-1β, and TNF-α, leading to excessive inflammation response." (PMID 28042205, 2016). "Follow-up experiments will be required for understanding the relative contributions of these two mechanisms in eliciting the net IL-1β response observed during sepsis." (PMID 27382187, 2016). "Given the importance of C5a-C5aR1 interactions in promoting the onset and development of sepsis, we sought to investigate the regulation of IL-1β production by C5aR1 signaling in a TLR4-mediated, mouse endotoxemia model." (PMID 27382187, 2016).
Sepsis (continued). "MT-2 up-regulated Akt phosphorylation and abrogated the increase of IL-1β and IL-6 mRNA expression from macrophages that stimulated with burn sepsis serum." (PMID 26550025, 2015). "Some antioxidants such as MitoQ, MitoE, and melatonin can reduce IL-1β and IL-6 levels and decrease NFκB activation, effect observed in a rat model with acute LPS sepsis." (PMID 26457108, 2015). "In models of murine melioidosis, it has been established that increased expression of IL-1β and IL-6 follow B. pseudomallei dissemination and coincide with acute sepsis and mortality." (PMID 26114445, 2015). "IL-1β mediates inflammatory and proliferative effects in many experimental models of lung injury, including sepsis, ventilator-induced lung injury, and bleomycin." (PMID 26611795, 2015). "TNF-α is widely accepted as the initial mediators in the pathogenesis of sepsis; it plays a key role in endogenous inflammation to induce IL-1β and IL-6 production during the early phase of CLP." (PMID 26273145, 2015). "Host responses to infectious challenge result in the excessive release of inflammatory mediators, such as TNF-α and IL-1β, which triggers the pathophysiological abnormities of sepsis." (PMID 26149595, 2015). "In apparent contrast, in experimental sepsis induced by cecal ligation and incision, levosimendan did reduce high plasma levels of IL-1β." (PMID 25888356, 2015). "To evaluate the degree of onset of systemic inflammation in mice with S. aureus-induced pneumonia, we measured the level of IL-1β and IL-6 in blood as the representative cytokines for systemic induction of sepsis." (PMID 26333035, 2015). "In conclusion, we have found that the alternations in the genotype and allele frequency of IL-1β (−511C/T), TNF-α (−308 G/A), TNF-α (−238 G/A) and IL-10 (−1082 G/A) genes are associated with an higher risk of sepsis development in trauma patients and outcomes." (PMID 26561011, 2015). "In line with our in vitro observations, we found a selective down-modulation of IL-1β levels in the course of endotoxin sepsis whereas other pro-inflammatory cytokines remained unaffected by the treatment." (PMID 26152605, 2015). "Previously published studies on sepsis show that high iNOS expression is associated with inflammatory mediators, such as TNF-α, IL-1β, NF-κB, and COX." (PMID 26174316, 2015). "It has been reported that DM (12.5 mg/kg, i.p.)inhibits inflammatory mediators, including cytokines (TNF-α, IL-1β and IL-6) and chemokines in sepsis mice model." (PMID 26391752, 2015). "The IL-1β, TNF-α and IL-10 polymorphism frequency was significantly higher in the post traumatic septic group than in the non-sepsis and appeared to be an independent risk factor for death due to septic shock." (PMID 26561011, 2015). "We detected that sepsis stimulates an over 2-fold increase in accumulation of the active form of caspase 1, resulting in a nearly 2000-fold induction of IL–1β generation, and Mito-Vit-E profoundly suppressed both events." (PMID 26448624, 2015). "Both Mito-Vit-E and TLR9 inhibitor OND-I repressed LPS-induced up-regulation of MYD88, RAGE, ASC, activated caspase 1 and IL–1β, confirming that sepsis induces a mtROS dependent mtDNA-TLR9 pathway in cardiomyocytes." (PMID 26448624, 2015). "Analysis of cytokine levels by multiplex array showed a rapid, sustained, and significant increase of the putative markers of experimental sepsis, namely IL-1β, IL-6, IL-10, and TNF-α, in FIP mice over a 24-hour period (p < 0.001) versus the sham group." (PMID 24725742, 2014). "Although these isolated observations support a potential role for the NLRP3 inflammasome/caspase-1/IL-1β pathway, the present study is the first to provide a systematic assessment of this pathway in endotoxemia/sepsis both in vivo and in vitro." (PMID 25216263, 2014). "In the present study, we provide evidence indicating that the NLRP3 inflammasome in CFs is activated in sepsis and increases IL-1β production." (PMID 25216263, 2014).